IL10 (interleukin 10)
Diseases named in the same sentence as IL10 in open-access papers (continued):
Sharing a sentence is not in itself a finding about the gene and the disease.
tumor (continued). "The ARG-1 mRNA level in tumor blocks, the frequency of Tregs, and IL-10 level were not affected." (PMID 27246354, 2016). "In our investigation, the FcγRIIlow/− activated B cells, without additional stimulation, could secrete IL-10 to repress tumour-specific cytotoxic T-cell response." (PMID 27853178, 2016). "Generally, the immune systems of tumor patients often have excessive inhibitory functions, which are induced by regulatory T cells (Tregs), myeloid-derived suppressor cells (MDSCs), or the secretion of immunosuppressive cytokines, such as tumor growth factor-β (TGF-β) and interleukin-10 (IL-10)." (PMID 27413764, 2016). "This increase in IL-10 tumor expression was not noticed in tumors from mice treated with PGE2." (PMID 27388564, 2016). "However, in human HCC tumours, the FcγRIIlow/−, but not the FcγRIIhigh, B cells actively and directly produced IL-10, suggesting the immune cellular networks between humans and mice are very different." (PMID 27853178, 2016). "The tumor and its stroma produce factors that attract immature myeloid cells, which in turn produce cytokines such as tumor-growth factor-beta (TGF-β), interleukin-10 (IL-10), arginase I and myeloperoxidase that prevent myeloid cell maturation and decrease lymphocyte activation." (PMID 28536390, 2016). "Therefore, we hypothesize that HLA-E is highly expressed in NB tissue, inhibits NK cells, and promotes the release of IL-10 and TGF-β1 to affect tumor growth." (PMID 27322426, 2016). "However, as the stimulus induced by CD28 tumor-targeting promotes Th1 cytokines (IFN-γ, TNF-α) but it also promotes the immunosuppressive cytokines (IL-10), we reasoned that, in order to have an antitumor effect, the immunosuppressive environment should be diminished." (PMID 26992239, 2016). "It is known that, in addition to STAT3, cytokines like IL-6 and IL-10, VEGF, and Oncostatin M are able to activate other pathways such as PI3K/AKT and Ras/MAPK that govern fundamental processes, such as cell proliferation, differentiation, metabolism, and tumor survival." (PMID 25695042, 2015). "Large amounts of transmitters, such as M-CSF, IL-6, IL-10, TGF-β, and COX-2, induce transformation of TAMs into M2 macrophages that secrete immune inhibitory chemokines with poorer antigen presenting and cytotoxic abilities, leading to tumor growth and metastasis." (PMID 26167490, 2015). "Type 2 cytokines, including IL-4 and IL-10, downregulate the tumor-specific immune response by directly suppressing the production of Th1 cytokines, which prevents CTL and NK cell activation and by inhibiting tumor antigen presentation by antigen-presenting cells." (PMID 25352158, 2015). "In addition, Tregs may exert their immunosuppressive effects by both directly interacting with tumor cells via the expression of surface molecules such as CTLA-4, and via the secretion of cytokines such as IL-10 and TGF-β43." (PMID 26394925, 2015). "Lastly, similar to the potential off-target effects of IL-10, whether or not a tumor arises in a pro-inflammatory or anti-inflammatory environment also becomes a key consideration in modulating TGF-β." (PMID 26217588, 2015). "The function of Bregs from tumor tissues was not examined because the MFI of CD24 was decreased in IL-10+ B cells, less than in IL-10− B cells from tumor (P < 0.05) and few CD24hiCD38hiBregs were detected in tumor tissues, as confirmed by newly published research." (PMID 26378021, 2015). "However, levels of IL-1α, IL-4, IL-10, IL-13, and TNFα were not significantly altered by tumor growth." (PMID 26347589, 2015). "Furthermore, the production of high levels of IL-10 and transforming growth factor-β1 (TGF-β1) by malignant cells reduces ovarian production of interferon-γ (IFN-γ) and TNF-α, suppressing the immune response against the tumor cells." (PMID 25624918, 2015). "However, there is no study to determinate the relationship between ILT4 and IL-10 expression in tumor tissues and assay their role in tumor progression." (PMID 24762057, 2014).
tumor (continued). "Here, mature dendritic cells present tumor-specific antigens to peripheral naive FoxP3+ Treg cells, which then proliferate in situ and are thereafter capable of suppressing the anti tumor immune response of CD8+ effector T-cells through heterogeneous mechanisms including IL-10 and TGF-ß." (PMID 25365237, 2014). "Within the tumor microenvironment, in the absence of Rip2, we found a cytokine signature enriched in IL-4 and G-CSF, polarizing towards a M2 phenotype as reflected in increased production of IL-10 and arginase-1." (PMID 24733360, 2014). "Finally, emerging evidence suggests that MDSCs may promote immune-escape also by suppressing NK activity, overexpressing programmed death ligands (PD-L1 and PD-L2) and releasing IL-10 and indoleamine 2,3-dioxygenase (IDO) in the tumor microenvironment." (PMID 25538892, 2014). "Their immunosuppressive functions can be exerted by secretion of cytokines (e.g., IL-10 and TGF-β), through inhibitory receptors (e.g., CTLA-4 and PD-L1) via cell contact, and secretion of amino-acid depleting enzymes (arginase and IDO) in the tumor microenvironment." (PMID 24967214, 2014). "Besides, IL-10 can also impair secondary CD8+ T cell responses and thus inhibit tumor immunity." (PMID 24885636, 2014). "While IL-4 is a cytokine involved in Th2 responses (which are not appropriate for anti-tumor immunity), IL-10 and TGF-β are cytokines with immunosuppressive functions and thus could be involved in the pro-tumor activities of γδ T cells." (PMID 25538706, 2014). "In addition, these immunosuppressive cytokines IL-10 and TGF-β might not only suppress Th1 cell responses by tumor-infiltrating T cells but also favor the development of regulatory T cells." (PMID 24872958, 2014). "JSI-124 treatment confirmed the contact-dependency of STAT3 activation, as we have previously demonstrated that this JAK2 inhibitor selectively blocks contact-dependent STAT3 activation but not that induced by soluble factors, such as IL-10 or tumor cells conditioned media." (PMID 24073274, 2013). "In more recent studies using IL-10 and IL-10 receptor knockout and transgenic mouse strains, investigators reported that IL-10 directly mediated intratumoral activation and expansion of resident tumor-reactive CD8 T cells that independently rejected established tumor growth and progression." (PMID 23533029, 2013). "Alternatively, another group using IL-10 knockout mice showed that IL-10 indirectly hindered tumor development, growth, and progression by impeding the development of both MDSCs and CD4+ TReg cells which presumably contributed to immune suppression, carcinogenesis, and tumor pathology." (PMID 23533029, 2013). "Furthermore, the tumor microenvironment in general strongly favors the accumulation of Treg cells, the induction or recruitment of MDSCs, and a corresponding increase in expression of TGF-β1 and IL-10." (PMID 23935688, 2013). "Analyses of purified tumor-infiltrating CD45+ cells indicated that Lov treatment increased mRNA levels for M1 markers, which was statistically significant for IFNγ and IL-1β, whereas it downregulated M2-like markers (with significant differences for IL-10, CD206 and CCL22)." (PMID 24317954, 2013). "In the 16th week, the cytokines IL-10, IL-17, TGF-β and TNF-α were detected at the highest overall level, creating a chronic inflammation cytokine milieu that may lead to antitumour immunity eradication and accelerated tumour progression." (PMID 23176085, 2012). "To study the effects of pardaxin on tumor functions, we performed a real-time RT-PCR analysis of caspase-3, caspase-7, caspase-8, caspase-9, Bax, Bcl-2, STAT2, ATF3, STAT3, SOCS3, IL-2, cathelicidin, TNF-α, MyD88, NF-κB1, p65, IFN-β1, IFN-γ, IL-1β, IL-6, IL-7r, and IL-10." (PMID 23015777, 2012).
tumor (continued). "Indeed, analysis of IL-10 and TGF-β1 expression status in lymph nodes and tumors using qRT-PCR revealed strong IL-10 and TGF-β1 mRNA expression in tumor-draining lymph nodes in high tumor-burdened LLA-TG-3 mice compared to the low tumor burden group." (PMID 22674057, 2012). "In addition, IL-10 inhibits secretion of the proinflammatory cytokines by CD4+ T cells and impairs CD8+ T cells response, whereas tumor clearance can be enhanced in the absence of IL-10." (PMID 23176085, 2012). "As many tumor antigens are self-antigens, for example, differentiation antigens like tyrosinase-related protein 2 (TRP-2), tumors can escape immune surveillance by recruiting nTregs or by inducing regulatory T cells (iTregs) from naïve or effector T cells through release of IL-10 or TGF-β1." (PMID 22674057, 2012). "Indeed, we detected increased IL-10 and TGF-β1 mRNA levels in tumor-draining LN of LLA-TG-3 mice." (PMID 22674057, 2012). "Immunoregulatory cytokines such as IL-10 and TGF-β play an important role in immune tolerance, and it seems that suppressor effect of regulatory T cells (CD4+CD25+) on the development of tumor associated antigen-reactive lymphocytes is independent of cytokines." (PMID 22927872, 2012). "Therefore, the transient depletion of Treg, the blocking of IL-10 and TGF-β, the fine control of NKT-derived IFN-γ in the tumor microenvironment may enhance therapeutic HPV vaccine potency." (PMID 24212964, 2011). "To investigate why Pam2 lipopeptides could not induce effective anti-tumor responses against NK-sensitive tumors in vivo, we investigated whether Pam2 lipopeptides could activate suppressive factors, such as IL-10 and T reg -related molecules." (PMID 21533081, 2011). "Altogether, the results suggested that TBHsp70 could induce Tregs which correlated with the induction of IL-10 in the draining lymph node, and that was independent of the presence of tumor cells." (PMID 21170379, 2010). "While CSE caused a decrease of intracellular interferon gamma (IFN-γ) production and increase of IL-10 production by NK cells in all cases, the effects were not significant (IFN-γ: 10.4% vs. 5.6%, n = 5, p = 0.09, IL-10: 1.7% vs 11.5%, n = 5, p = 0.1) upon tumour challenge." (PMID 20107494, 2010). "In murine studies, CCL21-DC induced tumor regression, stimulated production of IFN-γ and the CXC chemokines MIG (CXCL9) and IP-10 (CXCL10) at the tumor site, and decreased local concentrations of immunosuppressive inflammatory mediators including IL-10, PGE2, and TGF-β." (PMID 18644162, 2008). "However, in the present study, when the analysis was confined to those patients with stage I disease, neither C-reactive protein, interleukin-6 or interleukin-10 appeared to normalise on resection of the primary tumour." (PMID 17003778, 2006). "This would be consistent with the observations in the present study that circulating interleukin-6 and interleukin-10 concentrations were not strongly correlated with tumour volume but were similarly correlated with each other before and after resection of the renal tumour." (PMID 17003778, 2006). "Cultures of tumor infiltrating lymphocytes secreted significantly higher amounts of IgM and IgG than the PBL of either patients or controls in good agreement with the increased levels of IL-2 and IL-10, since these cytokines are involved in B cell activation and enhance immunoglobulin synthesis." (PMID 15450122, 2004). "Additionally, HPV-infected cells can secrete immunosuppressive cytokines, such as interleukin-10 (IL-10) and transforming growth factor-beta (TGF-β), which inhibit the activation and proliferation of effector immune cells while promoting regulatory T cells (Tregs) that suppress anti-tumor immunity." (PMID 40006976, 2025).
tumor (continued). "In addition, they also indirectly shift the balance between tumor reactivity and tumor tolerance by recruiting through e.g. CCL3, CCL4, and CCL5 as well as be promoting the induction of T cell-suppressive Tregs through the release of IL-10 or TGF-β, among others." (PMID 40050933, 2025). "MSCs, often reprogrammed in tumors, may secrete immunosuppressive factors such as IL-10 and TGF-β, with EVs potentially enhancing this effect by delivering specific miRNAs or proteins that boost MSC immunosuppressive functions, thus facilitating tumor immune evasion." (PMID 40103824, 2025). "Furthermore, studies have demonstrated that ultrasound-excited 5-aminolevulinic acid (5-ALA) can inhibit tumor growth, promote the polarization of macrophages in the TME towards the M1 phenotype, and enhance the expression of cytokines interferon-gamma (INF-γ), TNF-α, and IL-10 in the TME." (PMID 40521198, 2025). "The anti-inflammatory cytokine IL-10 showed multiple positive correlations with metabolites such as glucosamine, D-tagatose, TMAO, caffeine, LPC 22:4, and LPC 20:1, suggesting these metabolites may contribute to immune suppression in the tumor microenvironment." (PMID 40361187, 2025). "During tumour progression, TAMs may be more inclined to the M2 polarized state and can secrete various growth factors such as VEGF, PDGF, EGF, chemokines and cytokines such as IL-10, TGF-β, CCL2 and CXCL12; thus, the tissue trophic function of M2-type TAMs instead promotes tumour progression." (PMID 39060648, 2024). "Similarly, macrophages in metastatic UVM showed strong enrichment for cytokines like Adiponectin, Prolactin, IL7, IL10, IL15, IL9, IL31, APRIL, Persephin, and IL22, highlighting their role in creating a pro-tumorigenic environment through immune modulation and support of tumor growth." (PMID 39916959, 2024). "In addition, increased mRNA levels of IL‐6 and IL‐10, as well as increased expression of PD‐L1, were observed in BMDMs cocultured with LLC‐shCx43 cells compared with LLC cells, indicating that knocking down Cx43 in tumour cells induced macrophages towards the protumor type." (PMID 39592436, 2024). "Thus collectively, even under the detrimental influences of tumor microenvironment, NLGP initiates an inflammation-favoring anticancer type 1 immune-commitment through upregulation of pro-inflammatory IL-12p70 and reduction of anti-inflammatory IL-10 secretion from murine dendritic cells." (PMID 38649988, 2024). "Furthermore, the anti-tumor immune response significantly weakens as the T-reg cells secrete cytokines (IL-10, TGF-β etc.)that suppress other types of immune cells such as helper and cytotoxic T cells, macrophages, natural killer cells that are responsible for anti-tumor responses." (PMID 38813084, 2024). "Considering the findings for M-MDSC, ARG1, soluble VISTA, Treg cells, IL-10, and soluble TIMD-4, it can be suggested that immunosuppression at the periphery has a significant impact, sustaining impaired systemic immunity, which may limit the anti-tumoral immune response at the tumor site." (PMID 39502689, 2024). "However, tumor infiltration by pDCs has been correlated with a poor prognosis for patients with various cancers, supposedly due to their impaired response to TLR7/9 activation and decreased IFN-α release, thereby contributing to the production of IL-10, TGF-β, and Treg cells." (PMID 36768258, 2023). "In addition, the factor(s) responsible for tumor-induced secretion of IL-10 is not known." (PMID 36830840, 2023). "Moreover, inflammatory cytokines secreted by the tumor, such as TGF-β, TNF-α, IL-1, IL-6, IL-8, and IL-10, could induce local inflammation and fibrosis, which affect the electrophysiological characteristics of adjacent myocardium of pulmonary veins and atrium, facilitating occurrence of AF." (PMID 37519821, 2023).
tumor (continued). "Therefore, the elevation of Il-10, Il-35, and Tgf-β in SRC-3 KO Tregs is expected to increase/stabilize the number of SRC-3 KO Treg cells in the spleen by autocrine signaling pathways that then support their later infiltration into tumors, leading to tumor eradication." (PMID 37253006, 2023). "It has been observed that Th2 cytokines such as IL10 can directly suppress DC-mediated antigen presentation and T cell activation; these observations have led to the longstanding hypothesis that CD4+ T cell Th2 polarization is a mechanism of tumor immune escape." (PMID 37830618, 2023). "However, if the WT1-332 peptide strongly induces immunosuppressive IL-10 production/secretion by HTLs, it may have a negative impact on the anti-tumor immune responses." (PMID 36672344, 2023). "Another investigation revealed that when a mouse tumor model was treated with genetically modified lactic acid bacteria designed to generate IL-10 or antioxidant enzymes, the CRC tumor development was inhibited, demonstrating that IL-10 might limit tumor progression." (PMID 38096329, 2023). "Therefore, IL-10 can regulate the TLR4/NF-κB pathway in dermal fibroblasts through the IL-10 receptor (IL-10R)/STAT3 axis to reduce both ECM protein deposition and fibroblast transformation to myofibroblasts, thereby inhibiting the formation of skin scar induced by lipopolysaccharide." (PMID 36873898, 2023). "Notably, IL-10 (p < 0.01), PD-L1 (p < 0.0001) and VEGF (p < 0.05) expression were significantly increased in TAMTRIB1-KD compared to MTRIB1-KD, suggesting the myeloid TRIB1 is an important regulator of oncogenic cytokine expression in TAMs, downstream of signals secreted by tumor cells." (PMID 35664073, 2022). "In addition to PD-L1, EVs transported to Mφs can promote the expression of cytokines IL-6, IL-10, and MCP-1 by activating the Janus kinase 2-signal transducer and activator of transcription 3 (JAK2/STAT3) pathway, leading to immunosuppression of Mφs and promotion of tumor development." (PMID 36032078, 2022). "In addition, IL-10 influences the expression of MHC class II molecules and CD86/CD80 in antigen-presenting cells, the expression of MHC class I molecules in tumor cells, the expression of costimulatory molecules on dendritic cells and regulates the IL-12 production." (PMID 34152493, 2022). "Additionally, these nanovesicles can carry TGFβ and IL‐10, the cytokines known to stimulate the conversion of conventional T‐lymphocytes into Treg cells which induce Treg expansion and enhance their functions to suppress antitumor CD8+ T cells responses to permit tumour growth as well." (PMID 35822529, 2022). "Furthermore, production of a regulatory cytokine such as IL-10 and TGF-β induce MHC class I chain related-proteins A (MICA) and B (MICB), CD95 and inhibitory enzymes such as Indolamine-2,3-dioxygenase 1 (IDO), by tumor and regulatory cells suppress the activity of NK cells." (PMID 35632488, 2022). "In addition, this capacity of MC-C tumor lysate was correlated to its high concentration of HGMB1 and Hsp60 – two recognized danger signals that favor DC maturation – and low concentration of IL-10 and TGF-β – two known immunosuppressive cytokines that inhibit DC maturation;." (PMID 35922755, 2022). "Corroborating this assumption, our data show that whole platelets, as well as tumour cell-induced releasates, evoked Treg differentiation from CD3/CD28/CD2 stimulated CD4+ T cells, although further cell types than regulatory T cells might contribute to IL-10 release from PBMCs." (PMID 35285006, 2022). "However, IL-10 did not have a direct effect on tumour cell migration." (PMID 33484377, 2021). "Dendritic cells loaded with TEXs in tumor-draining lymph nodes could promote the production of pro-inflammatory cytokines, then the level of IL-6, IFN-γ and IL-12 in the tumor microenvironment would become high, while the IL-10 was of a low level, which promoted the anti-tumor response of Th1." (PMID 33922480, 2021).